CD4 (CD4 molecule)
Diseases named in the same sentence as CD4 in open-access papers (continued):
Sharing a sentence is not in itself a finding about the gene and the disease.
infection (continued). "The kinetics of PD-1+ CD4+ T-cells during the acute erythrocytic-stage P. yoelii 17X(NL) infection are similar to those observed during P. chabaudi infection." (PMID 25628621, 2014). "In a longitudinal study, individuals who initiated ART within six months of infection had greater CD4/CD8 ratio increase compared to later initiators (>2 years)." (PMID 24831517, 2014). "Treatment of primary infection appeared to be effective in preserving the pool of CD4 cells in acute more than recent infection." (PMID 25397522, 2014). "The functional response after infection was further evaluated by examining their ability to stimulate CD4+ T cell proliferation and differentiation in a mixed lymphocyte reaction." (PMID 24918929, 2014). "The appearance of exhausted CD4 T cells at the chronic phase appears to be a consequence of the reduced primary CD4 response after infection with the transgenic/attenuated parasite." (PMID 24551250, 2014). "The correlation between the resistance to infection and the Th1 bias of CD4+ T cells has been identified in 5-LO−/− mice infected with other pathogens, including M. tuberculosis and T. gondii." (PMID 25165415, 2014). "Based on our results, we cannot get the conclusion that a lower CD4 cell count has a causal relationship with CRF01_AE as patients infected with a CRF01_AE subtype could have been diagnosed during a later stage of their infection than those infected with non-CRF01_AE subtype." (PMID 25333965, 2014). "We specifically examined CD4+ T cells, and observed that early-life AhR activation changed the proportion of functionally distinct CD4+ T-cell subsets responding to infection." (PMID 25051576, 2014). "The loss of fecundity was accompanied by reduced IFNγ expression by CD4+ T cells and a higher proportion of macrophages at the site of infection." (PMID 24586152, 2014). "Protective host immune responses to these infections initially requires the activation and expansion of pathogen-specific CD4 Th1 cells within lymphoid tissues and subsequent relocation of these effector cells to sites of infection." (PMID 25071779, 2014). "Only patients with subsequent infection exhibited a delay in the recovery of CD4+ T lymphocyte counts." (PMID 24597828, 2014). "At the highest concentration of CD4+ exosomes (∼800 ng/ml) a small (∼10%) inhibition of VSVG-MSCV infection was detected." (PMID 25423108, 2014). "The important role of CD4+ T-cells in the induction of the antibody response in ruminants following infection or vaccination with a virus or a viral peptide has been demonstrated." (PMID 25255918, 2014). "This demonstrates that CD28 signaling is required for the initiation of the CD4+ memory T cell response, in addition to being required throughout the primary immune response to infection." (PMID 25347065, 2014). "In the early infection, the CD4+ T cell can release IFN-γ, IL-2, and TNF-α, which can activate macrophages to fight against M. tuberculosis." (PMID 24741595, 2014). "Ad5hr infection also altered the adaptive immune system of the host, transiently increasing the frequency of activated T cells and CD4+ T cells expressing Treg markers in blood." (PMID 25203111, 2014). "The percentage of CD4+ T cells was significantly increased in the thymus of LP as an effect of the diet (p<0.001) and in LPi animals as a combined effect of diet and infection conditions (p<0.05)." (PMID 25535967, 2014). "Then, the virus rapidly migrates to the gut-associated lymphoid tissue, where it induces massive depletion of memory CD4+ T cells, and establishes a self-propagating infection in secondary lymphoid organs." (PMID 25028990, 2014). "Trans-infection of CD4+ T cells by HIV-1 captured on mDCs appears to be a particularly potent mechanism of viral transmission and is thus thought to play a major role in HIV-1 spread in lymphoid tissues in vivo." (PMID 25033082, 2014).
infection (continued). "In more recent studies, CD4 CTL generated in vivo in response to infection or vaccination and characterized ex vivo demonstrated that perforin mediated cytotoxicity was the dominant mechanism utilized by CD4 CTL." (PMID 24586481, 2014). "PBL or purified primary CD4+ T cells were infected with 400 ng/106 cells and cultured for 48 h, resulting in 10-12% infection rate as determined by measurement of the intracellular p24 expression using flow cytometry." (PMID 24586238, 2014). "The protracted infection of CD4+ T cell-depleted mice was confirmed by histological staining of liver sections for the LCMV nucleoprotein with the VL4 antibody, clearly showing more VL4-stained hepatocytes in CD4+ T cell-depleted mice." (PMID 24466045, 2014). "Nef, produced shortly after infection, enhances internalization of pre-existing CD4 from the cell surface and targets the receptor for lysosomal degradation." (PMID 24822052, 2014). "Viral load reached variable levels below the viral cutoff, but the infection appeared to be controlled only after the first three months when specific CD4+ T-cells appeared and a drop in viral load was observed." (PMID 25166270, 2014). "During the acute phase of the infection, CD4 T cell responses are critical to promote the induction of humoral immunity but dispensable for the induction of CD8 T cell responses." (PMID 25120535, 2014). "Preferential M133-specific effector CD4 T cell expansion also occurs in the natural infection because the ratio of M133-specific Tregs/T effector cells in the naïve precursor pool is 0.15 but this decreases to 0.02 in the infected brain." (PMID 25102154, 2014). "It was detected by 10NOS2−/− in 15.8±3.1% of CD4+CD44+ (p = 0.0041) at 1 month post infection, a response similar to that seen in NOS2−/− FP cells." (PMID 25210773, 2014). "In mice depleted of CD4+ T cells, infection with murine LCMV led to chronic infection, even in the presence of CD8+ T cells." (PMID 24795718, 2014). "We show that the dominant restriction is at early RT and that this infection block is determined by Env-CD4 interactions and can be rescued with VSV-G pseudotyping." (PMID 24656066, 2014). "Although it is widely believed that CD4+ T cells are the key lymphocyte subset that regulates anti-Leishmania immunity, studies utilizing low dose infections show that CD8+ T cells are also important for optimal primary immunity." (PMID 25412267, 2014). "Age influences HIV infection; the likelihood of seroconversion illness, mean CD4 count and time from infection to development of AIDs defining illnesses decreases with increasing age." (PMID 25397442, 2014). "Extensive studies with experimental mouse models infected with L. major have shown that the outcome of infection with Leishmania parasites is critically dependent on the activation of one of the two subsets of CD4 T cells, Th1 and Th2." (PMID 24624248, 2014). "In summary, CD4+ memory T-cell analysis revealed that infection with B. pertussis primarily generates specific Th1 and Th17 responses, regarded essential in protection against a B. pertussis infection." (PMID 25137043, 2014). "On this note, given the spatially separated and temporally distinct mechanisms exploited by Nef and Vpu to degrade CD4, it is likely that in the presence of Nef, the effect of Vpu cannot be adequately quantified during the 48-hour infection." (PMID 24498878, 2014). "CD3+ T cells as well as CD8+ and CD4+ cells dropped markedly on day 2 post-infection, with the reduction being most dramatic for CD8+ cells." (PMID 24968319, 2014). "Our results suggest that, in HIV-infected VNPs, decreased infection of CD4+ TCM and TSCM, cells are involved in preservation of CD4+ T cell homeostasis and lack of disease progression despite high viremia." (PMID 25167059, 2014). "At day 5 post-infection, endogenous CD4+ T cells in the cancer group had an inhibitory receptor profile consistent with phenotypic exhaustion with increased expression of BTLA and 2B4." (PMID 24796533, 2014).
infection (continued). "Severe PEM can lead to leucopenia (decreased number of white blood cells), decreased Th cell (CD4+) and cytotoxic T cell (CD8+) numbers, as well as a reduced CD4+:CD8+ ratio—considered an important correlate of susceptibility to infection." (PMID 27417487, 2014). "Levels of SIV peak in plasma 14~21 days after infection of macaques, followed by gradual reductions in peripheral CD4 T cells." (PMID 25364618, 2014). "As expected, at later time points of infection, significant increases in the amount of CD4 and CD8 T cells in the lymph nodes and ears of C57BL/6 and BALB/c groups were noted." (PMID 24967701, 2014). "HIV-1 influences T-cell function and homeostasis throughout the course of infection leading to quantitative effects within the CD4 T-cell population and qualitative effects in both CD4 and CD8 T cells." (PMID 25333710, 2014). "It has been shown that CD4+CD25+Foxp3+-deficient mice are hyperactive to intestinal commensal flora and would develop IBD triggered by infection." (PMID 25475342, 2014). "The overall expansion in CD4+ T-cell number after infection is likely also influenced by intrinsic and extrinsic factors because this effect was retained in reciprocal transfers." (PMID 25051576, 2014). "Further, we found that the turnover of resting CD4+ T cell SIV DNA was higher for escape during early infection than for escape later in infection (p = 0.0084)." (PMID 24710023, 2014). "Nevertheless, we previously observed that RGH infection of activated primary CD4+ T-cells from three donors results in a high degree of direct non-productive infection, comparable to Jurkat cells." (PMID 24502247, 2014). "Host cell infection begins with the interaction of the gp120 subunit of the viral envelope glycoprotein (Env) complex with CD4." (PMID 25423108, 2014). "Our data shows that following primary infection in all subjects, peripheral C. jejuni-specific CD4+ T cells produce pro-inflammatory cytokines, including IFNγ and TNFα, peaking 7-14 days post-infection." (PMID 25397604, 2014). "In contrast, C57BL/6 mice required depletion of both CD4+ and CD8+ T cells for infection and papillomatosis, and separate CD4 knock-out and CD8 knock-out C57BL/6 were also resistant." (PMID 25121947, 2014). "These lymphocytes are the major responding T cell subset in the lung of mice infected with F. Tularensis bacterium, releasing large amounts of IL-17a during the early stages of infection whereas CD4+ T cells start to produce this cytokine later." (PMID 25330249, 2014). "Among the CD3+ cells, the CD8 T cells preferentially profit from the recruitment-function of MC, as can be seen by comparing the CD8/CD4 T-cell ratios in different compartments after infection of WT C57BL/6 mice and the congenic “sash” mutants." (PMID 24763809, 2014). "Although resting CD4 T cells are refractory to infection in vitro, local environmental factors within lymphoid and mucosal tissues such as cytokines facilitate viral replication while maintaining the resting state." (PMID 25330112, 2014). "Perhaps infection of macrophages or dendritic cells is important for promulgating the infection of the small numbers of CD4+ CCR5+ lymphocytes remaining in the gut." (PMID 24465411, 2014). "Whereas high dose infection induced strong CD4+ T cell proliferation and Th1 cytokine response, low dose infection predominantly activates CD8+ T cells." (PMID 25412267, 2014). "It has to be noted that CD4 epitopes are less well defined than CD8 epitopes in the context of HIV-1 natural infection, hence in silico predictions of CD4 epitopes are less accurate than those for CD8 epitopes." (PMID 25350851, 2014). "The percentage of FoxP3+CD4+ T cells observed at day 20 post infection (p.i.)was reduced in the lungs and spleen of M. bovis BCG infected mice compared to non-infected controls." (PMID 25050936, 2014).
infection (continued). "In this report, we used the Lamina Propria Aggregate Culture (LPAC) model to identify the PCD pathway(s) triggered in primary LP CD4+ T cells ex vivo by infection with an R5 tropic HIV-1 strain." (PMID 24495380, 2014). "Upstream of T-cell–dependent antibody production, infection initiated CD4+ T-cell differentiation into several subpopulations of conventional effector cell subsets." (PMID 25051576, 2014). "In a human infection model, carriage of S. pneumoniae increased the prevalence of CD4+IL-17A+TNF+IFN-γ+ Th cells in lungs and blood, as compared to non-carriers." (PMID 25119879, 2014). "The smaller the proportion of CD4+ T cells, the more likely that the animals will develop a serious infection." (PMID 24916952, 2014). "During the 2nd infection in S mice, initial CD4 T cells levels were recovered, but CD8 T cells remained in lower number and proportion than in uninfected mice." (PMID 24465641, 2014). "Tissue immunofluorescence revealed the presence of some CD4 T cells in follicular areas, particularly at one month after infection and during the chronic phase." (PMID 24763747, 2014). "So it is possible that an apparent transmission event involving CD4+ cells actually resulted from an initial infection of epithelial cells." (PMID 25010677, 2014). "Changing the capacity of CD4+ T cells to differentiate into distinct effector subsets has major implications on the progression and resolution of infection." (PMID 25051576, 2014). "The frequency of baseline CD4+T cell count <200 was higher and the frequency of CD4 T counts >500 lower in CRF01_AE infection than CRF07_BC infection." (PMID 24586795, 2014). "Another postulated theory is the formation of adenovirus-specific antibody immune complexes that activate both dendritic and CD4+ T cells hence fuelling infection." (PMID 25202303, 2014). "Partial depletion of CD4 T cells, or the administration of neutralizing anti-IL-4 antibody, close to the time of infection with 106 parasites, modulates the response from a Th2 to Th1 mode, resulting in resistance." (PMID 24684592, 2014). "A prediction arising from this is that turnover of SIV DNA within resting CD4 T cells would be higher during early infection, when viral levels are typically high." (PMID 24710023, 2014). "This suppression resulted in the blocking of SIV reverse transcription in CD4+ T-cells thereby preventing the initial burst of virus replication and thus protecting macaques from infection." (PMID 25071760, 2014). "Although potentially confounded by a number of factors, this finding is consistent with a model in which low-intensity STH infection confers a beneficial effect on CD4 count." (PMID 25101890, 2014). "The total CD4+T cell count at the end of the simulated 11-year period (1 year post-infection plus an additional 10 years) is approximately 173 cells/ μL." (PMID 24945407, 2014). "In immunophenotypic CVL studies, increases in CD5+ T lymphocytes and subsets of CD4+ and CD8+ T lymphocytes were reported and related to a profile associated with possible resistance against infection by L. infantum." (PMID 24507702, 2014). "Knowledge about the infection, CD4 T lymphocytes and HIV-ribonucleic acid values were measured before and after this program." (PMID 25642197, 2014). "In 127 patients with the HIV/HCV-infection, the percentage of CD4+cells before the CHC treatment was >25% and more (Group 1 [Gr." (PMID 25394139, 2014). "Absolute cell numbers of CD4+ T-cells and eosinophils increased with infection time, while macrophage, neutrophil and B-cell numbers remained at similar levels between 35 and 100 dpi." (PMID 24663956, 2014). "The interaction of HIV-1 with CD4+ exosomes would result in a reduction of unbound Env proteins available to interact with CD4 molecules on the surface of host cells, thus hindering infection." (PMID 25423108, 2014). "Collectively, these results indicate that depletion of CD4+ T-cells in RMs results in massive activation and infection of microglia." (PMID 25356757, 2014).
infection (continued). "A similar trend was observed in the pattern of in vivo turnover of memory CD4+ and CD8+ T-cells and TREC depletion in naive CD4+ T-cells, although naive T-cell turnover was relatively unaffected by either infection." (PMID 24803534, 2014). "We report that in primary CD4+ T cells, the flux through the glycolytic pathway is increased upon infection with HIV-1." (PMID 25421745, 2014). "Infection with HIV is characterized by a progressive decrease of CD4+ T lymphocytes and immune dysfunctions that ultimately lead to AIDS." (PMID 25081906, 2014). "The increase of CD4+T cell was only observed in the late infection (14 days post infection), while the increase of CD8 + T cells was observed from day 10 to 14 days post infection." (PMID 24666970, 2014). "Consider a peripheral self-antigen, continuously present at a low level, against which, following an acute infection, some antibody has been produced, and some CD4 T cells have been generated." (PMID 24684567, 2014). "In the AP, patients with severe infections had the highest median level of IL-17+CD4+ cells (p < 0.05 for all comparisons)." (PMID 24646014, 2014). "After primary Ad5hr infection there was an increased frequency of activated CD4+ T cells in blood, although the levels of these cells quickly returned to baseline." (PMID 25203111, 2014). "Consistent with the in vivo data, the HSV-2 infected vaginal tissues had higher frequency of α4β7high memory CD4+ T cells than the control tissues 3 days after infection." (PMID 25521298, 2014). "A similar IL10-dependent functional impairment of CD4+ T cells has been described in other infections such as HIV that are characterized by chronic high-level antigen stimulation." (PMID 24415936, 2014). "The presence of intraepithelial DCs, capable of sampling the “outside” and to rapidly bring and transfer the virus to neighbor CD4 T cells and activate them seems to be pivotal to infection establishment." (PMID 25250026, 2014). "Overall, we show that Treg depletion and infection strongly promotes the expansion, activation and maturation of effector CD4+ and CD8+ T cells with simultaneous increases in IFN-γ production by both subsets." (PMID 25108672, 2014). "Consistent with prior studies of SIV/SHIV infection in RMs, the absolute number of peripheral CD4+ T-cells was decreased following infection and partially restored on ART." (PMID 25254512, 2014). "Several factors such as duration of infection, age, male gender, consumption of alcohol, HIV infection and low CD4 count have been associated with fibrosis progression rate." (PMID 25394140, 2014). "The interaction of Tat with cellular RNA requires an intact RNA binding domain and Tat RNA binding is linked to an increase in RNA abundance in cell lines and during infection of primary CD4+ T cells by HIV." (PMID 24990269, 2014). "We observed that, under the standard scenario STD, commencement of therapy at earlier stages of the infection always resulted in higher final total CD4+T cell counts than commencement of therapy at later stages of the infection." (PMID 24945407, 2014). "An important role of CD4+ T cells during infection is aiding in the formation of a robust virus-specific antibody response." (PMID 25051576, 2014). "The level of CD4+ cell counts (median 228 cells/μL: range 202–380 cells) did not influence the cure rate (P = 0.23) or the reduction in the intensity of the infection (P = 0.37)." (PMID 25671125, 2014). "The cluster of variables that were positively correlated with FIV [-] animals included blood CD4+ T cell levels at weeks 8 and 12 post-infection, cortical neuronal counts, body weights, and performance in the object memory test." (PMID 24886384, 2014). "Once infection is established, the course of disease progression in vertically infected infants is generally faster than in adults, with a rapid decline of CD4 cells and onset of recurrent infections, failure to thrive, and delayed neurodevelopment." (PMID 25161656, 2014).